CDH5 (cadherin 5)
Diseases named in the same sentence as CDH5 in open-access papers (continued):
Sharing a sentence is not in itself a finding about the gene and the disease.
infection (55 papers, 2012 to 2025). The state of being infected such as from the introduction of a foreign agent such as serum, vaccine, antigenic substance or organism. "While not strongly impacting tight junction expression at low MOI, Eta variant at MOI 0.1 induced 26.5% median decrease of CDH5 expression after 6 days of infection." (PMID 37537664, 2023). "Eta variant at MOI 1 also transiently induced an increase in tight and adherens junction expression at 2 dpi (median increase for TJP1: 33.5%; F11R: 38.3%; OCLN: 25.9%; CLDN5: 96.6% and CDH5: 74.5%) before expression levels returned to the uninfected condition ones after 6 days of infection." (PMID 37537664, 2023). "CDH5 is one of the main components of endothelial adhesion and connection, which maintains the integrity of the endothelial barrier and controls the migration of leukocytes during injury and infection." (PMID 33391332, 2020). "The third cluster included genes that were moderately expressed in CDH5+ cells, highly expressed in c-KIT+ populations, and associated with ontology terms such as development of the hematopoietic program, leukocyte migration, chemotaxis, and response to infection/wounding ontology terms." (PMID 25466247, 2014). "(B) Lentiviral infection efficiency of MCF-7 cells stably depleted of STARD13, CDH5, HOXD1, and HOXD10 was verified by Western blot analysis." (PMID 29848346, 2018). "(A) Lentiviral infection efficiency of MDA-MB-231 cells stably expressing STARD13-3′UTR, CDH5-3′UTR, HOXD1-3′UTR, and HOXD10-3′UTR was examined by qRT-PCR." (PMID 29848346, 2018). "The results of the present study as well as previous studies suggest that Cdh5 and Cldn5 are major determinants of BBB deterioration during infection, while Wnt/β-catenin signaling may contribute to the maintenance of BBB integrity." (PMID 32509459, 2020).
retinopathy (6 papers, 2016 to 2026). "To assess the role of these downstream players in retinopathy, we expanded our studies using mice treated with tamoxifen at P12 to specifically delete TSAd expression in endothelial cells, Sh2d2afl/fl; Cdh5-CreERT2 (denoted Sh2d2a iECKO)." (PMID 32312382, 2020).
adenocarcinoma (3 papers, 2009 to 2020). A common cancer characterized by the presence of malignant glandular cells. "In the GC sample cohort from the TCGA (Stomach adenocarcinoma (TCGA, Firehose Legacy, n = 478)), the levels of several markers for macrophages (FN1, MRS1, CD68, and CCL7), blood vessels (CDH5) and lymphatic vessels (VEGFC) exhibited positive correlations with TGM2 expression." (PMID 32467608, 2020).
CDH5 also shares sentences with these, for which no sentence is quoted: hepatocellular carcinoma (25 papers); ovarian carcinoma (19); diabetic retinopathy (13); colon cancer (9); acute respiratory distress syndrome (8); pancreatic cancer (7); prostate carcinoma (7); rheumatoid arthritis (7); Obesity (6); viral infection (6); cardiovascular disease (5); lung injury (5); triple-negative breast carcinoma (5); bacteremia (4); breast tumors (4); cerebral cavernous malformation (4); dengue (4); Hydrocephalus (4); neurological disorders (4); pulmonary edema (4); acute myocardial infarction (3); angina (3); bacterial infection (3); colitis (3); cutaneous melanoma (3); diabetes type 2 (3); diabetic nephropathy (3); edema (3); endotoxemia (3); inflammation (3).
A further 169 diseases each share a sentence with CDH5 in 3 papers or fewer.